PEF1 (penta-EF-hand domain containing 1)
Description:
Calcium-binding protein that acts as an adapter that bridges unrelated proteins or stabilizes weak protein-protein complexes in response to calcium. Together with PDCD6, acts as a calcium-dependent adapter for the BCR(KLHL12) complex, a complex involved in endoplasmic reticulum (ER)-Golgi transport by regulating the size of COPII coats. In response to cytosolic calcium increase, the heterodimer formed with PDCD6 interacts with, and bridges together the BCR(KLHL12) complex and SEC31 (SEC31A or SEC31B), promoting monoubiquitination of SEC31 and subsequent collagen export, which is required for neural crest specification. Its role in the heterodimer formed with PDCD6 is however unclear: some evidence shows that PEF1 and PDCD6 work together and promote association between PDCD6 and SEC31 in presence of calcium. Other reports show that PEF1 dissociates from PDCD6 in presence of calcium, and may act as a negative regulator of PDCD6. Also acts as a negative regulator of ER-Golgi transport; possibly by inhibiting interaction between PDCD6 and SEC31 (By similarity).
Synonyms: ABP32; PEF1A
Tractability: Antibody: UniProt places it where antibodies can reach, with high confidence. PROTAC: UniProt records ubiquitination sites on it; ubiquitination databases record sites on it; its protein half-life has been measured.
Gene: Protein-coding gene on chromosome 1 (31,629,866 to 31,644,896, reverse strand). Ensembl gene ENSG00000162517.
Subcellular location: Cytoplasm; Endoplasmic reticulum; Membrane; Cytoplasmic vesicle, COPII-coated vesicle membrane
Subcellular location (Human Protein Atlas): Nucleoplasm; Vesicles; Cytosol
Gene Ontology:
Molecular function: calcium-dependent protein binding; identical protein binding; protein binding; protein dimerization activity; protein heterodimerization activity; RNA binding; ubiquitin-like ligase-substrate adaptor activity; calcium ion binding
Biological process: COPII vesicle coating; endoplasmic reticulum to Golgi vesicle-mediated transport; neural crest cell development; neural crest formation; positive regulation of protein monoubiquitination; response to calcium ion
Cellular component: COPII vesicle coat; Cul3-RING ubiquitin ligase complex; cytoplasm; cytosol; extracellular exosome; membrane; endoplasmic reticulum; ER to Golgi transport vesicle membrane
Genetic constraint (gnomAD): Loss-of-function variants: 17 observed, 32.39 expected, observed/expected ratio (o/e) 0.52, 90% interval 0.36 to 0.79. The upper end of that interval is the gene's LOEUF score, 0.79, which puts it in group 3 of 6, group 1 being the genes least tolerant of losing a copy. Missense variants: 343 observed, 357.77 expected, observed/expected ratio (o/e) 0.96, 90% interval 0.88 to 1.05. Synonymous variants: 119 observed, 135.31 expected, observed/expected ratio (o/e) 0.88, 90% interval 0.76 to 1.02.
Homologues: Orthologues: chimpanzee PEF1 (100% identical), macaque PEF1 (99% identical), pig PEF1 (93% identical), dog PEF1 (93% identical), rabbit PEF1 (93% identical), guinea pig PEF1 (86% identical), mouse Pef1 (85% identical), rat Pef1 (82% identical), tropical clawed frog pef1 (70% identical), zebrafish pef1 (58% identical), Caenorhabditis elegans clp-8 (17% identical), Caenorhabditis elegans clp-1 (12% identical), and 5 more. Paralogues in human: CAPN11 (29% identical), CAPN2 (28% identical), CAPN8 (28% identical), CAPN1 (27% identical), CAPN3 (27% identical), SRI (27% identical), CAPN9 (27% identical), GCA (25% identical), CAPN12 (24% identical), CAPN14 (23% identical), CAPN13 (21% identical), CAPNS1 (19% identical), and 8 more.
Diseases named in the same sentence as PEF1 in open-access papers:
PEF1 is named in the same sentence as 2 diseases in open-access papers, as found by Europe PMC text mining. Sharing a sentence is not in itself a finding about the gene and the disease. The quoted sentences say what the papers report.
tumor (1 paper, 2019). "Both PEF1 and PEF2 treatments reduced tumor growth and prolonged the life span of the mice, however, the PEF2 protocol was more efficient." (PMID 31717542, 2019). "The PEF1 protocol induced a significant delay in tumor growth, however a complete response was not achievable." (PMID 31717542, 2019).
PEF1 also shares sentences with these, for which no sentence is quoted: infection (2 papers).